RNU105B (RNA, U105B small nucleolar)
Synonyms: E1-2; 105B
Gene: Small nucleolar RNA gene on chromosome 20 (8,831,186 to 8,831,393, forward strand). Ensembl gene ENSG00000201348.
Gene Ontology:
Biological process: RNA processing
Cellular component: nucleolus
Homologues: Orthologues: chimpanzee SNORA73 (98% identical), macaque SNORA73 (94% identical), dog SNORA73 (72% identical), mouse Gm25139 (66% identical), guinea pig SNORA73 (64% identical), mouse Gm25483 (62% identical), guinea pig SNORA73 (62% identical), mouse Gm25804 (60% identical), rabbit SNORA73 (58% identical), guinea pig SNORA73 (42% identical). Paralogues in human: SNORA73A (85% identical), SNORA73B (84% identical), SNORA73 (76% identical), SNORA73 (75% identical), RNU105C (74% identical), SNORA73 (67% identical), SNORA73 (38% identical).